MAGEB18 (MAGE family member B18)
Description:
May enhance ubiquitin ligase activity of RING-type zinc finger-containing E3 ubiquitin-protein ligases. Proposed to act through recruitment and/or stabilization of the Ubl-conjugating enzyme (E2) at the E3:substrate complex.
Synonyms: MGC33889
Tractability: No criterion of Open Targets' tractability assessment is met for any kind of drug.
Gene: Protein-coding gene on chromosome X (26,138,343 to 26,140,736, forward strand). Ensembl gene ENSG00000176774.
Subcellular location: Cytoplasm
Gene Ontology:
Molecular function: protein binding
Biological process: negative regulation of transcription by RNA polymerase II
Cellular component: nucleus; cytoplasm
Homologues: Orthologues: chimpanzee MAGEB18 (99% identical), macaque MAGEB18 (94% identical), pig MAGEB18 (75% identical), dog MAGEB18 (69% identical), mouse Mageb18 (57% identical), rat Mageb18 (57% identical), zebrafish ndnl2 (23% identical), Drosophila melanogaster MAGE (18% identical). Paralogues in human: MAGEB1 (52% identical), MAGEB10 (52% identical), MAGEB4 (51% identical), MAGEB17 (50% identical), MAGEB3 (49% identical), MAGEB2 (48% identical), MAGEB16 (47% identical), MAGEA10 (46% identical), MAGEB6B (43% identical), MAGEB6 (43% identical), MAGEC2 (41% identical), MAGEA11 (41% identical), and 25 more.
Diseases named in the same sentence as MAGEB18 in open-access papers:
MAGEB18 is named in the same sentence as 1 disease in open-access papers, as found by Europe PMC text mining. Sharing a sentence is not in itself a finding about the gene and the disease. The quoted sentences say what the papers report.
melanoma (1 paper, 2021). A malignant, usually aggressive tumor composed of atypical, neoplastic melanocytes. "The expression of MAGEB18 affects cell proliferation and apoptosis in melanoma." (PMID 33718161, 2021).